INS (insulin)
Diseases named in the same sentence as INS in open-access papers (continued):
Sharing a sentence is not in itself a finding about the gene and the disease.
type 2 diabetes (continued). "In a meta-analysis of nine studies, adherence to the MD was shown to significantly reduce levels of glycated haemoglobin (HbA1c), fasting glucose and insulin among patients with type 2 diabetes." (PMID 32354060, 2020). "Amyloid deposits involving insulin fibrils have been observed both in patients with type II diabetes, in normal aging and after repeated insulin injections." (PMID 32629793, 2020). "Polycystic ovaries, testosterone levels, paternal metabolic syndrome (MBS) and type 2 diabetes mellitus (T2DM)-related defects in insulin secretion and action are all genetic factors for PCOS." (PMID 32256454, 2020). "In type II diabetes, insulin is still produced by pancreatic cells but its interaction with IR1 fails to induce glucose uptake, leading to insulin resistance." (PMID 33209247, 2020). "This retrospective cohort study included 127 600 adults aged 21 to 89 years with type 2 diabetes at 4 health care delivery systems who initiated insulin therapy from January 1, 2000, through December 31, 2013." (PMID 31977057, 2020). "Glucagon-like peptide 1 (GLP-1) mimetics have been approved as an adjunct therapy for glycemic control in type 2 diabetic patients for the increased insulin secretion under hyperglycemic conditions." (PMID 32079069, 2020). "In summary, defective mitochondrial function is likely to have effects contributing to impaired insulin secretion in type 2 diabetes and, conceivably, in those cases of type 1 diabetes where detectable beta cell mass remains." (PMID 32894309, 2020). "Type 2 diabetes (T2D) is a heterogeneous condition characterized by impaired insulin secretion in response to glucose stimulation and development of insulin resistance." (PMID 32847122, 2020). "For mothers with severe obesity, the effect size of type 2 diabetes on their offspring having any ICD-10 F code diagnosis was between those of mothers with insulin-treated pregestational diabetes and gestational diabetes." (PMID 32031649, 2020). "Hu Yuankui reported that Wuling capsule advanced the peak of insulin secretion and prompted the recovery of β-cell function through a test of 34 patients with Type 2 diabetes after oral administration of Wuling capsule for one month." (PMID 31894843, 2020). "Recently, an unusually high potential to personalize type 2 diabetes management has been attributed to the use of continuous glucose monitoring tools and automated insulin delivery systems (i.e. artificial pancreas)." (PMID 33198734, 2020). "An increase in the plasma level of free fatty acids and their uptake by cells in type II diabetes further reduces the insulin-dependent absorption of glucose." (PMID 32911736, 2020). "When used in the treatment of type 2 diabetes, metformin is a good drug that increases tissue insulin sensitivity in patients with PCOS." (PMID 32992734, 2020). "Participants with frailty were more likely to have type 2 diabetes with complications, longer duration of type 2 diabetes, higher use of medications, higher use of insulin or sulfonylureas, and more comorbidities." (PMID 32596419, 2020). "The subgroup of type 2 diabetes patients who received intensive conservative insulin treatment had significantly lower CgB levels compared to those with other regimens of antidiabetic therapies (p = 0.0283)." (PMID 32684986, 2020). "In the present study, insulin treatment during pregnancy was a strong predictor for both type 1 and type 2 diabetes, which is in agreement with several earlier studies." (PMID 32725280, 2020). "Further, we identified genetic sharing between peripheral insulin signaling-related traits: type 2 diabetes with ‘aggressive taboo thoughts’, and levels of fasting insulin and 2 h glucose with OCD." (PMID 32341337, 2020). "After oral administration of PDBW at 400 mg/kg body weight daily for 8 weeks, the mice with type 2 diabetes showed significant decrease in the levels of fasting blood glucose and glycated hemoglobin A1c (HbA1c), and increase in the insulin level." (PMID 33043040, 2020).
type 2 diabetes (continued). "In our study, plasma galectin-9 levels in patients with obesity comorbid type 2 diabetes significantly increased and positively correlated with weight, BMI, hipline, UA, and especially islet-related indicators insulin and C-peptides." (PMID 33123595, 2020). "Maintenance of skeletal muscle insulin sensitivity and metabolic flexibility, through healthy diet and exercise, prevents or delays the development of type 2 diabetes." (PMID 31825657, 2020). "It has been long known that obese individuals, type-2 diabetics, and individuals who are insulin-resistant have skeletal muscle mitochondrial-defects." (PMID 32153503, 2020). "The resistance of insulin is responsible for the majority of defects that lead to the development of type-II diabetes mellitus." (PMID 32063933, 2020). "Biological components in coffee, such as caffeine, chlorogenic acids, lignans, and antioxidants, have been suggested to play a role in regulating insulin and glucose, which influence the process of developing type 2 diabetes." (PMID 32722593, 2020). "Our results suggest that cardiovascular outcomes and mortality should not be a motivating factor in the decision to start human vs analogue insulin therapy in insulin-naive adults with type 2 diabetes." (PMID 31977057, 2020). "As a result, alterations in either muscle mass and/or responsiveness to insulin action can lead to the development of type 2 diabetes both in mice and humans." (PMID 33199701, 2020). "Insulin therapy in patients with type 2 diabetes is often initiated with a single daily injection of basal insulin." (PMID 33202616, 2020). "Daily consumption of three cups of the green/roasted coffee blend (35/65), providing 445 mg of CGA/day, has shown beneficial effects against type 2 diabetes, lowering fasting glucose levels and insulin resistance, and increasing insulin sensitivity." (PMID 32872136, 2020). "A recent review suggested a disturbed insulin sensitizing action of adiponectin along with APPL1 as a major factor in type 2 diabetes." (PMID 32059381, 2020). "A number of studies have examined the association between type 2 diabetes (T2D) and FTD, with some suggesting that impaired insulin secretion, glucose intolerance and hyperglycaemia are risk factors." (PMID 31396860, 2020). "The present study aims to elucidate the effects of ethanol extract and butanol fraction of S. platensis on insulin release and glucose homoeostasis in type 2 diabetic rats, together with their mechanism of actions." (PMID 32517842, 2020). "Even the suppressed mitochondrial biogenesis and impaired mitochondrial activity have been reported to occur in skeletal muscle of young, lean, normoglycemic, insulin-resistant offspring of parents with type 2 diabetes mellitus (T2DM)." (PMID 32855652, 2020). "Long-standing Type 2 diabetics require high doses of insulin and the practice of giving BHI 30 thrice daily is thought of as a means of intensifying glucose control when use of insulin analogs is not feasible." (PMID 32448382, 2020). "A previous study showed that insulin-treated individuals with type 2 diabetes had higher Pittsburgh Sleep Quality Index and poor sleep quality." (PMID 32671413, 2020). "As for the strengths of this study, this is the first report investigating the association of total plasma N-glycome with metformin, statin, ACE inhibitors/ARB, SU derivatives and insulin use in type 2 diabetes." (PMID 32616483, 2020). "This systemic overabundance of proinflammatory cytokines in adipose tissue, including IL-6, activates STAT3 and subsequently AMPK leading to alterations in insulin signaling and eventually Type 2 diabetes." (PMID 32878032, 2020). "Among the 8 (42.1%) out of 19 cases previously diagnosed with type 2 diabetes, 6 (31.6%) cases involved insulin users." (PMID 32337291, 2020). "Glutamic acid decarboxylase antibodies (GADA) are a marker of autoimmune beta‐cell damage and are one of the major predictors of progression to insulin therapy in type 2 diabetes." (PMID 32318630, 2020).
type 2 diabetes (continued). "Recent studies have shown that both type 1 diabetes (T1D) and type 2 diabetes (T2D) are characterized by a deficit in ß-cells, a pancreatic endocrine cell that secretes insulin." (PMID 31929591, 2020). "It is quite likely therefore that the current line of clinical action in the field of type 2 diabetes has limited success largely because it is based on a misinterpretation of glucose-insulin relationship." (PMID 33365205, 2020). "Insulin-induced hypoglycemia is a major limiting factor in maintaining optimal blood glucose in patients with type 1 diabetes and advanced type 2 diabetes." (PMID 33042003, 2020). "The International Diabetes Federation states that type-2 diabetes is a chronic condition that occurs when there are raised levels of plasma glucose, attributed to insufficient/lack production of insulin, or because the body cannot use the insulin it produces." (PMID 33132909, 2020). "Inhibition of CPT1 is considered as a possible mechanism to modulate altered energy metabolism and improve insulin sensitivity of cells upon type II diabetes." (PMID 32911736, 2020). "This retrospective study aimed to compare pregnancy outcomes in women with preexisting type 2 diabetes receiving metformin or standard insulin treatment." (PMID 32887578, 2020). "Type 2 diabetes patients treated with insulin showed lower circulating sRAGE levels than type 2 diabetes patients not treated with insulin (429.87 ± 185.19 versus 557.03 ± 217.32 ng/L, P < 0.001)." (PMID 33187505, 2020). "Type 2 diabetes mellitus (T2D) is a complex metabolic disease that is characterized by insulin resistance and impairment of insulin secretion, which leads to hyperglycemia." (PMID 32174972, 2020). "For example, insulin replacement therapy used in patients with type 1 and type 2 diabetes seeks to replace insulin that would normally be produced by beta cells." (PMID 32382023, 2020). "The physiological importance of islet-derived GLP-1 and GIP in insulin secretion has been previously studied, where their contribution to the regulation of β-cell mass is debated in the pathophysiology of type 1 and type 2 diabetes (T1&T2DM)." (PMID 32090124, 2020). "Similar to the periphery, the central nervous system is sensitive to insulin in healthy humans, but can become insulin resistant in a number of conditions, including obesity, type 2 diabetes and neurodegenerative diseases." (PMID 33047031, 2020). "Clinical trials have demonstrated that oral magnesium supplementation improves insulin sensitivity, glucose homeostasis, and HbA1c levels in patients with type 2 diabetes." (PMID 33322540, 2020). "In particular, protective effects of MFE on beta cells of the pancreas are closely associated with the antidiabetic actions of MFE, potentially suggesting that insulin-dependent type 2 diabetes is curable." (PMID 32454931, 2020). "A larger RCT would be useful to allow causal comparisons to be made between telemonitoring-supported care of type 2 diabetes during transition to insulin and conventional care." (PMID 32406854, 2020). "This study aimed to compare the efficacy of post-meal walking with one prandial insulin on glycemic control in type 2 diabetic patients who failed basal insulin therapy." (PMID 32236116, 2020). "Mild hypoglycemic episodes during the continuing insulin dose reduction period indicate a long-term drug-free euglycemic remission in patients with newly diagnosed type 2 diabetes." (PMID 32149152, 2020). "MAPK4K4 also plays an important role in insulin resistance in response to glucose stimulus for the development of type II diabetes mellitus." (PMID 32993798, 2020). "The included study population comprises healthy controls, insulin-resistant, and type 2 diabetes participants with a high heterogeneity between studies." (PMID 32256572, 2020). "Many animal studies and further clinical data have revealed that reduced PI3K activity can play a role in insulin sensitivity and type II diabetes." (PMID 32076626, 2020).
type 2 diabetes (continued). "It has been appreciated for decades that the incretins are responsible for 50–70% of the insulin release following an oral glucose challenge, while this dramatically drops to ~20% in people with type 2 diabetes." (PMID 33195459, 2020). "Insulin-naive adults with type 2 diabetes who initiate and continue treatment with human vs analogue insulins had similar observed rates of major cardiovascular events, CVD mortality, and overall mortality." (PMID 31977057, 2020). "Type 2 Diabetes Mellitus (T2DM) is an insulin independent metabolic disease characterized by chronic hyperglycemia and concomitant insulin resistance and it is estimated that greater than 415 million adults worldwide have T2DM." (PMID 33141822, 2020). "There is marked heterogeneity in the rate of progression to insulin requirement in patients with type 2 diabetes (T2D)." (PMID 32722720, 2020). "The other disadvantages of endogenous insulin secretagogues in the treatment of type 2 diabetes are also their peptidyl nature, which requires administration by injection." (PMID 33153226, 2020). "The IMI‐DIRECT study assessed the association between time to insulin requirement and PRS (derived from 61 type 2 diabetes risk variants)." (PMID 32318630, 2020). "Majority (57.8%) rated their confidence in prescribing insulin as “low” and only 23.4% had ever prescribed outpatient insulin for type 2 diabetes in their practice." (PMID 32611395, 2020). "This is consistent with our previous studies in mice with a range of perturbations recapitulating various aspects of insulin resistant type 2 diabetes." (PMID 32401607, 2020). "The type 2 diabetes (T2D) is an integrated and multifactorial metabolic disorder that is characterized by insulin resistance and reduced secretion of insulin from pancreatic beta cells." (PMID 32210733, 2020). "Bariatric surgery improves insulin sensitivity and secretion in patients with type 2 diabetes, but the effect on patients with prediabetes or even normal glucose tolerance deserves further consideration." (PMID 32314253, 2020). "In humans, the decrease in fasting insulin has been shown to be proportional to the number of years an individual has had type-2 diabetes." (PMID 32153503, 2020). "In this context it is further worth mentioning that the male study cohort was more strongly affected by obesity-related diseases, particularly insulin dependency in type 2 diabetes." (PMID 33192409, 2020). "The fasting C-peptides levels are found to be average between type 1 and type 2 diabetes; however, the circulating insulin levels at baseline and post-stimulation with insulin secretagogue are lower compared to obese patients." (PMID 32399348, 2020). "For example, 70 mg efruxifermin dosed weekly, corresponding to two pharmacokinetic half-lives, appeared to improve HOMA-IR, fasting glucose, and fasting insulin in type 2 diabetes patients." (PMID 33381084, 2020). "Disruption of circadian rhythm has been shown to lead to metabolic dysregulation, including Type-2 diabetes (T2D) and insulin-sensitivity." (PMID 32938639, 2020). "It was also significantly associated with many endocrine traits (e.g., Insulin sensitivity index, FDR = 0.042; Type 2 Diabetes, FDR = 0.049)." (PMID 32680461, 2020). "The insulin signaling system is considered to be a common link in the pathogenesis of type 2 Diabetes." (PMID 32664584, 2020). "For example, in Cohort A, but not Cohort B, a relationship was observed between the genera Lactobacillus and Ruminococcus and insulin resistance, a key feature of type 2 diabetes pathogenesis." (PMID 32956361, 2020). "Her father died at the age of 79, he had type 2 diabetes requiring insulin treatment, renal and hepatic cysts detected at ultrasonography and normal renal function." (PMID 32457805, 2020). "Further studies in patients living in the community as well as inclusion of individuals with type 2 diabetes with insulin monotherapy are warranted." (PMID 32317650, 2020).